EDN1 (endothelin 1)
Diseases named in the same sentence as EDN1 in open-access papers (continued):
Sharing a sentence is not in itself a finding about the gene and the disease.
Stroke (continued). "In a stroke model induced by injection of endothelin-1, the MSC-exo selectively targets the damaged area, while in other pathologies such as AD models of transgenic mice (5xFAD), they were found mainly in regions of the hippocampus." (PMID 32807217, 2020). "These mice are microinjected with endothelin-1 (ET-1) in the left medial prefrontal cortex (mPFC) to induce a small (~1 mm3) unilateral stroke affecting the left infralimbic (IL), prelimbic (PL), and cingulate gyrus (CG) regions." (PMID 32999279, 2020). "Endothelin-1 is a vasoconstrictor, and its role in strokes has been described in a mouse model of strokes." (PMID 32751801, 2020). "Accordingly, it is preferable to create focal ischemia using the photothrombotic (PT) or endothelin-1 (ET-1) stroke models, which are both highly recommended by recent international consensus panels." (PMID 32848875, 2020). "As the first proof-of-concept study in NHPs to test in vivo cell conversion technology, we employed a focal stroke model through intracranial injection of endothelin-1 (ET-1) to induce blood vessel constriction in the motor cortex of Rhesus Macaque monkeys." (PMID 33224952, 2020). "In agreement with the previous studies, the present study also showed that astrocytic endothelin-1 overexpression promotes astrogenesis which contributes to more severe ischemic brain injury in murine models of stroke during the first week." (PMID 31733648, 2019). "Dl-NBP has been shown to promote neurological functional recovery in stroke rats in an endothelin-1-induced focal permanent ischemic stroke model." (PMID 32038259, 2019). "Another experimental model of stroke is based on the application of endothelin-1, a peptide that presents potent and long-lasting vasoconstrictive properties." (PMID 31635068, 2019). "Taken together, these findings indicated that astrocytic endothelin-1 overexpression promoted neural progenitor cell proliferation and differentiation into astrocytes via the Jak2/Stat3 pathway in murine models of stroke." (PMID 31733648, 2019). "In rats trained to consume alcohol prior to endothelin-1-induced (ET-1) stroke in the MCA territory, there was a greater preference for alcohol than that of sham animals." (PMID 30034335, 2018). "The IKVAV-injectable hydrogel with rheological elastic shear moduli below 1.0 kPa was implanted together with human eSCs-derived cortical progenitors into the lesion cavity of stroke rats (endothelin-1 model)." (PMID 30966220, 2018). "Whitehead and colleagues found that giving a vasoconstrictor, endothelin-1 (ET-1), to adult AβPP Tg mice results in a stroke with increased AβPP and tau-2 expression by 8 days post-stroke." (PMID 30249297, 2018). "We set out to address this gap by a multimodal in vivo study of neurovascular recovery from endothelin-1 model of cortical focal-stroke in sham vs. ovariectomized female rats." (PMID 30271324, 2018). "Kilic and coworkers, in a publication not involving cancer, had shown that melatonin markedly inhibits the levels of endothelin-1 (ET-1) in the brain of patients suffering from a stroke." (PMID 28420185, 2017). "To find out to what extent far-remote brain regions are affected after stroke, we used a bilateral endothelin-1-induced prefrontal infarct rat model." (PMID 26973455, 2016). "The model of stroke chosen for this study was the endothelin-1 model of conscious stroke in rats based on recent quantification and characterization of multiple remodeling events shown to be similar to that in humans." (PMID 26927079, 2016). "Microinjection of male C57/BL6 mice with endothelin-1 (ET-1, 1600 pmol) induced a small (1 mm3) stroke consistently localized within the left mPFC." (PMID 27483381, 2016). "Pre-differentiated GABAergic neurons, undifferentiated SVZ-hNSCs or media alone were stereotaxically transplanted into the rat brain (n=7/group) 7 days after endothelin-1 induced stroke." (PMID 26420220, 2015).
Stroke (continued). "Ischemic stroke was induced in rats by peri-vascular application of the vasoconstrictor endothelin-1 and forebrains were collected at 1, 3, 6 and 24 hours post-stroke." (PMID 24858129, 2014). "Endothelin-1-induced stroke resulted in neurological deficits detected between 1 and 7 days (P<0.001), but significant recovery was observed beyond this time." (PMID 24809543, 2014). "In the present study, we have used a multiparametric approach to validate on middle-aged rats the widely used endothelin-1 model of unilateral stroke carried-out usually in young rats." (PMID 24245542, 2013). "In a study most similar to ours, 11-week-old Pet-ChR-YFP mice (which express YFP exclusively in 5-HT neurons) were treated once daily with 18 mg/kg fluoxetine via drinking water for 6 weeks starting a week after an endothelin-1–induced stroke in the medial prefrontal cortex." (PMID 38355299, 2024). "The endothelin-1 model has the advantage of generating highly reproducible lesions and controlled and persistent deficits in upper limb function, making it useful for studying post-stroke recovery strategies." (PMID 38540276, 2024). "Endothelin-1 injection induces relatively small infarcts, similar to lacunar strokes (i.e., strokes induced by blockage of small blood vessels), and it is possible that blocking microglial phagocytosis is more beneficial in such small strokes since there is less damage and debris to be removed." (PMID 35216419, 2022). "Therefore, we investigated the role of HDAC1 in stroke by using a rat model of endothelin-1-induced brain ischemia." (PMID 34381129, 2021). "Experimental stroke models, such as tMCAo, pMACo, photothrombiotic stroke, and endothelin-1 induced ischemia, may have various pathological and cellular contexts which lead to different activation programs." (PMID 33757565, 2021). "The endothelin-1 model of focal stroke is based on the local application of exogenous endothelin-1 (ET-1), a potent and long-active vasoconstrictive peptide, which induces stroke and cell death after sustained vasoconstriction with reperfusion." (PMID 34943816, 2021). "In a study designed to determine the specific migration of EVs in different mice models of pathology, the EVs were shown to home on relevant areas, such as migration to the area of injection in an endothelin-1 model of stroke, and the hippocampus in a transgenic 5XFAD model of Alzheimer’s52." (PMID 32873780, 2020). "Overall, the findings of the present study further confirmed our hypothesis that astrocytic endothelin-1 overexpression promotes neural progenitor cell proliferation and differentiation into more astrocytes after stroke via the Jak2/Stat3 pathway." (PMID 31733648, 2019). "However, the exact mechanism through which astrocytic endothelin-1 affects the Jak2/Stat3 pathway in a murine stroke model need would benefit from further investigation in the future." (PMID 31733648, 2019). "Of note, vascularization is important to stroke recovery, and physical activity helps to maintain cerebrovascular activity and integrity, and promote cerebral blood flow during reperfusion, probably through the expression of endothelin-1 (ET-1)." (PMID 30941660, 2019). "Endothelin-1 (ET-1) is synthesized and upregulated in astrocytes under stroke." (PMID 31733648, 2019). "Therefore, future animal work on the subject using more mobile and adaptable stroke methods such as endothelin-1 (ET-1) or photothrombosis will be required to test this." (PMID 30034335, 2018). "For example, a fast-gelling injectable in situ hydrogel mixture of HA modified with acetic hydrazide through carbodiimide chemistry and methylcellulose (MC), favored nSCs engraftment in the damaged brain, enhancing post-stroke motor recovery in an endothelin-1 mouse stroke model." (PMID 30966220, 2018). "The stroke group of rats was infused with endothelin-1 and the sham group was infused with saline." (PMID 28566754, 2017).
Stroke (continued). "To produce a focal stroke in the mPFC, we used the endothelin-1 (ET-1) model." (PMID 27483381, 2016). "Increased levels of CCL5, CCL2, CCL3, and CXCL12 found in the early phase of endothelin-1 induced stroke model were not the cause of neurodegeneration." (PMID 27635404, 2016). "Ischaemic stroke was induced in the sensorimotor cortex representing each rat’s dominant forearm, using standard methods to induce focal vasoconstriction using endothelin-1 (Solemanet al., 2010,2012)." (PMID 26614754, 2016). "Here, we explored the patterns of microglial activation, astrocytosis, oligodendrocyte damage, myelin impairment, and Nogo-A immunoreactivity between 3 and 30 postlesion days (PLDs) after experimental striatal stroke in adult rats induced by microinjections of endothelin-1 (ET-1)." (PMID 28090244, 2016). "After hypoxic/ischemic brain injury, endogenous vasoconstrictor endothelin-1 (ET-1) levels are elevated leading to exacerbated brain injury, but when melatonin is administered in mice stroke models a beneficial neuroprotective effect was observed inhibiting ET-1." (PMID 27932976, 2016). "The endothelin-1 model is the only model of stroke in animals that avoids the use of general anesthetics and their neuroprotective side effects, which may account for the lack of effect observed in the striatum with apocynin." (PMID 23401848, 2013). "To study the behavior of Wnt3a over-expression in an ischemic environment, we used the endothelin-1 ischemia model Endothelin-1 is a potent vasoconstrictor that has been used to induce ischemic injury resembling a thrombo-embolic stroke event when injected directly into rodent brain." (PMID 22815838, 2012). "They suggest that these model variants in BMP6 are the strongest risk factors, whereas variants in EDN1 are associated with stroke through BMP6 and ANXA2 but are not as relevant for the risk prediction." (PMID 20401335, 2009). "Moreover, it has been reported in stroke that the release of interleukine-6 (IL-6), a marker of inflammation, is enhanced by tPA through activation of NMDARs and upregulation of endothelin-1 (ET-1) and c-Jun N-terminal kinase (JNK)." (PMID 36142247, 2022). "A study using endothelin-1-induced cerebral ischemia in rats (ET-1 model) showed that infiltrated neutrophils are phagocytized by macrophages in the first 3 days after stroke onset, but MPO activity keeps increasing, suggesting that MPO may not be the best measurement for neutrophil accumulation." (PMID 31849964, 2019). "Even more, endothelin-1 application has been shown to induce proliferation of astroglia, producing a permissive milieu for enhanced axonal sprouting, which may interfere with post-stroke recovery mechanisms." (PMID 28064357, 2017). "Both EDN1 and BMP6 are on chromosome 6 (at 6p24.1 and 6p24.3, respectively), and their association suggests that this chromosomal region may be associated with an increased risk of stroke." (PMID 20401335, 2009). "To assess the role of HDAC1 in microglial activation following ischemic stroke, we adopt a rat stroke model of endothelin-1 injection and performed HDAC1 knock down in the cerebral cortex by concurrently stereo-microinjection of endothelin-1 and HDAC1 siRNA." (PMID 41388741, 2025). "That said, several stroke models have been studied including permanent and transient MCAO using endothelin-1 (ET-1) or the intraluminal filament models." (PMID 33059037, 2020). "Wild-type rats subsequently received an endothelin-1 (ET1) subcortical stroke and were imaged at days 7 and 28 post-stroke before immunohistochemistry of TSPO, GFAP, iNOS, and the MHCII rat antigen, OX6." (PMID 32990808, 2020). "It has been shown that acute administration of calcitriol—given 4 h after stroke induced by endothelin-1 and then every 24 h for 5 consecutive days— failed to improve cerebral damage or neurobehavioral functions." (PMID 40791737, 2025).
Stroke (continued). "This study delves into the intriguing relationship between post-stroke alterations and ASICs, specifically focusing on postsynaptic ASIC1a enhancement in the amygdala following prefrontal cortex (PFC) ischemia induced by endothelin-1 (ET-1) injection." (PMID 38137132, 2023). "By contrast, parenchyma topical application of vasoconstrictor endothelin-1 did not generate significant stroke damage or neuroinflammatory cell activity." (PMID 36279013, 2022). "The National Institutes of Health Stroke Scale (NIHSS) score and endothelial function index level such as plasma nitric oxide (NO), human endothelin-1 (ET-1), and vascular endothelial cell growth factor (VEGF) were compared before and after treatment between the two groups." (PMID 34354551, 2021). "In contrast, a blend of HA and MC injectable hydrogel, that was tested in the same stroke rodent model (endothelin-1), did not result in better survival of cerebrally transplanted iPS-derived neuroepithelial stem cells." (PMID 30966220, 2018). "Since ischemia develops slowly after endothelin-1 application and is accompanied only by minimal edema, this model again does not accurately mimic human stroke." (PMID 28064357, 2017). "Here we investigate the effect of stroke severity on angiogenesis and SVZ cell proliferation and migration after cerebral ischemia using the endothelin-1 (ET-1) rat model of stroke, and correlate these findings with infarct volume, inflammation, scar formation and functional recovery." (PMID 24809543, 2014). "The review will contrast and compare different experimental stroke models used to study CIDS, focusing on four of the most common models used currently: middle cerebral artery occlusion (MCAO), photothrombotic stroke (PTS), endothelin-1 (ET-1), and hypoxia-ischemia (HI)." (PMID 31635068, 2019).
cardiac hypertrophy (164 papers, 2007 to 2025). "The myocardial hypertrophy associated with endothelin-1 is relatively minor, although with high concentrations the increase in wall thickness is sustained weeks after treatment." (PMID 39767621, 2024). "Because of its phosphorylatio, inhibition of GSK3β is associated with cardiac hypertrophy in response to endothelin-1 or phenylephrine." (PMID 33240671, 2020). "Paradoxically, another study reported that cardiac hypertrophy in AhR−/− mice was caused by pressure overload and accompanied by evident fibrosis and elevated expression of plasma endothelin-1 (ET-1) and angiotensin II (Ang II)." (PMID 29984241, 2018). "Cardiac hypertrophy, induced by neurohumoral factors, including angiotensin II and endothelin-1, is a major predisposing factor for heart failure." (PMID 29872396, 2018). "Proteomic research has revealed that several molecular targets are associated with pathologic cardiac hypertrophy, including angiotensin II, endothelin-1 and isoproterenol." (PMID 24877123, 2014). "Hyperuricemia is associated with myocardial hypertrophy and remodeling mediated via an endothelin-1 pathway." (PMID 24117726, 2013). "The initiation of hypertrophic stimuli for myocardial hypertrophy has been described through mechanical stress and neurohumoral mechanism that are associated with the release of factors such as angiotensin II (Ang II), endothelin-1 (ET-1) and norepinephrine." (PMID 29872396, 2018). "Finally, it has been established that endothelin-1 (ET-1) is implicated in cardiac hypertrophy and, ultimately, in heart failure, mainly due to its function as a growth factor in a variety of cells, such as vascular smooth muscle cells, cardiac myocytes, and fibroblasts." (PMID 38097805, 2023). "Pathological cardiac hypertrophy is usually triggered by mechanical pressure overload or neuroendocrine hormones such as Ang II, endothelin 1, and catecholamines." (PMID 40610735, 2025). "Cardiovascular regulating factors that participate in cardiac hypertrophy; exemplified by angiotensin II (Ang II), endothelin-1 (ET-1) and catecholamines (α-adrenergic), bind to G protein coupled receptors (GPCR)." (PMID 39820183, 2025). "For example, nitric oxide (NO) secreted by ECs alleviates cardiac hypertrophy through the NO-sGC-cGMP pathway, while endothelin-1 (ET-1) and neuregulin-1 (NRG-1) secretion promote hypertrophy." (PMID 40940801, 2025). "A further mechanism by which chronic hyperleptinemia can promote ventricular hypertrophy and fibrosis is via increasing endothelin-1 (ET-1) production." (PMID 39682585, 2024). "The CCOs successfully modeled cardiac hypertrophy by exhibiting thickened chamber walls, reduced fractional shortening, and increased myofibrillar disarray upon treatment with endothelin-1 (EDN1)." (PMID 39935786, 2024). "Sarpogrelate has been reported to suppress Ang II-, endothelin-1- or phenylephrine-induced cardiac hypertrophy in cultured cardiomyocytes in addition to attenuating systolic dysfunction in mice subjected to transverse aortic constriction." (PMID 38786079, 2024). "CCOs can be modified to recapitulate aspects of cardiac disease through administration of endothelin-1, a vasoconstrictor and known inducer of cardiac hypertrophy." (PMID 39767621, 2024). "Previous studies have shown that diacylglycerol kinase zeta (DGKζ) can suppress cardiac hypertrophy by inhibiting the diacylglycerol (DAG)-PKC pathway in response to mechanical strain or growth agonists such as endothelin-1 (ET-1)." (PMID 38250603, 2024). "The increase in blood pressure due to endothelin-1 can be seen to increase the left ventricular pressure and induce cardiac hypertrophy." (PMID 38786079, 2024). "This increases the expression of endothelin-1 (ET-1), leading to uncontrolled AH and subsequent organ damage, namely, cardiac hypertrophy." (PMID 36902291, 2023).